CD14 (CD14 molecule)
Diseases named in the same sentence as CD14 in open-access papers (continued):
Sharing a sentence is not in itself a finding about the gene and the disease.
cancer (continued). "Independent of the cancer cell line used, monocytes failed to upregulate CD1c and only showed a small increase in CD14 expression in response to cancer cell line-derived cues." (PMID 38242119, 2024). "Indeed, we show that the inflammatory signature of CXCL-iFibro is functionally relevant, as CXCL-iFibro are able to attract CD14+ monocytes and to polarize them into FOLR2+ macrophages, which have been recently described in cancer and diabetic kidney." (PMID 38272907, 2024). "Comparing the response groups, the proportions of Macro_NLRP3 and Mono_CD14 significantly increased in the R group across many cancer types, whereas no obvious proportional changes were observed in the NR group." (PMID 39034339, 2024). "These included cancer-relevant proteins such as MMP14 and CD14." (PMID 39020428, 2024). "Although changes of phenotypes were not fully identical in MKN45 and NCI-N87 cells, our results showed that CD14 and ILK1 could participate in regulating critical biological behaviors of cancer cells during metastasis which were outgrowth and EMT." (PMID 37568802, 2023). "MDSCs in cancer patients were characterized by the expression of CD14, CD11b, CD33, and Arg1, along with low or absent expression of HLA-DR." (PMID 37865804, 2023). "Thus, we determined the incidence of CD14+ monocytes, and CD68+, CD163+ and MAC387+ TAMs in the cancer tissues of HCMV+ IBC patients." (PMID 35847899, 2022). "Because PD-L1-negative EpCAM+ cancer cells, low PD-1 expressed CD8+T cells, and remarkably increased CD14+CD68+CD163+TIM-3+ macrophages were observed in MPE with disease progression, TIM-3 blockade therapy might be applicable to treatment." (PMID 36293034, 2022). "CCL3 is secreted in CD14+ bladder CSCs rather than CD14− cancer cells, and macrophage infiltration is also increased in the TME." (PMID 35740975, 2022). "This shift is notable given that the percentage of CD14+ cells appears to decrease between the non-irAE cancer patients and the mild case before rising again in the severe irAE population." (PMID 36358824, 2022). "The number of CD14+ cells was significantly higher in cancer tissue than in normal control for both inflammatory infiltrates (p < 0.0001) and the stroma (p < 0.0001)." (PMID 33625532, 2021). "Furthermore, in the vast majority of solid cancer models, M2-like Mφs and/or TAMs at the cancer site differentiate in situ from circulating CCR2+CD14++CD16– classical monocytes, recruited via cancer cell-secreted CCL2." (PMID 34249942, 2021). "Our spectral cytometry data show that they are distinct from the recently defined CD14+ DC3 population, and that they are present in the circulation of healthy donors, SARS-CoV-2-infected patients, as well as patients with five different types of cancer." (PMID 34394090, 2021). "There is now a large body of evidence linking CD14+HLADRlo/neg monocytes to systemic immune suppression and paralysis and their negative affect on cancer immunotherapy." (PMID 31191529, 2019). "To test the hypothesis that the S100A9+ MDSC-derived macrophages can protect cancer cells from EGFR-TKI killing, we isolated CD14+ monocytes from PBMCs and induce them into macrophages (monocytes-derived macrophages, MDMs)." (PMID 29484139, 2018). "Across all subtypes, we found that dual positive (CD14+/CCR2+) cells were almost three times more abundant in the stromal (pan-CK negative) regions than in the cancer cell islet (pan-CK positive) regions." (PMID 29777108, 2018). "In cancer settings, CD14+ MDSCs have been shown to be the dominant suppressive populations of MDSCs, and correlated with cancer incidence, whereas G-MDSC did not correlate with clinical outcomes, even though both subsets were increased." (PMID 28498847, 2017). "All cell types were negative for haematopoietic cell markers CD45, CD34, CD19, CD14, human lymphocyte antigen-DR (HLA-DR), the carcinoma cell marker (c-MET) and EPCAM." (PMID 28419140, 2017).
cancer (continued). "Anti-cancer vaccination without information of T cell epitopes will become feasible, based on genetically modified CD14-ML-DC expressing antigenic proteins." (PMID 27050553, 2016). "Information on T cell epitopes is not necessary in vaccination with cancer antigen-expressing CD14-ML-DC; therefore, all patients, irrespective of HLA type, will benefit from anti-cancer therapy based on this technology." (PMID 27050553, 2016). "In another recent study sunitinib reduced non-classical CD33+ CD14+ CD16+ MDSCs in the blood of cancer patients by apoptosis and the rest of CD33+ CD14+ CD16+ MDSCs showed less pSTAT3, ArgI and less suppressive activity on T-cell proliferation." (PMID 27886105, 2016). "Thus, we believe that HER2 expression on CD14+ or CD56+ cells is indicative of contact between immune cells and HER2+ cancer cells." (PMID 25655677, 2015). "Here, in a larger cohort of subjects including both volunteers and cancer patients, CD4+ cells segregated distally from the CD14+HLA-DRlo/neg phenotype and were inversely correlated to the percentage of CD14+HLA-DRlo/neg monocytes (p < 0.001; Spearman r = -0.3244)." (PMID 25512872, 2013). "In addition we now show an increased frequency of the CD14+ DDC subset among DC migrating from IL-10- and cancer-conditioned skin." (PMID 23875023, 2013). "Using DC vaccine as an anti-cancer therapy module has been facilitated by the development of methods to generate DCs from proliferating CD34+ precursors or from non-proliferating CD14+ monocytes." (PMID 22013914, 2011). "In a related study, DCs from cancer patients generated from CD14+monocytes by culturing with GM-CSF and IFN-α, but without IL-4 secreted higher levels of IL-10 (Th2 response), compared with IL-4 and GM-CSF generated DCs." (PMID 18588665, 2008). "CD14 expression was mainly identified in immune cells rather than cancer cells." (PMID 37568802, 2023). "In addition, we previously found high infiltration of CD14+ monocytes in IBC cancer tissues compared to non-IBC." (PMID 35847899, 2022). "Because THP‐1 is a cancer cell line and previous reports have shown that some inflammatory genes are conversely regulated in PMA‐differentiated THP‐1 cells and MDMs,59 human peripheral blood CD14+ monocytes were used next to further examine the effect of IFN‐λ4." (PMID 33205487, 2021). "The flow cytometry analysisof ASCs revealed that more than 90% of all cancer andnormal ASCs were positive for the stem cell specificmarkers, including CD90, CD105, CD44 and CD73, butthey were negative for the expression of hematopoieticspecific markers, such as CD45, CD34 and CD14." (PMID 31721539, 2020). "In normal part of cancer samples, the expression of genes that negatively regulate the MyD88-independent TLR signaling pathway and genes that positively regulate prostaglandin E synthesis were enhanced in CD14+CD11c+CD163low cells compared to CD14−CD11c+ cells." (PMID 32076066, 2020). "Moreover, we demonstrated that CD14+ cells isolated from PDAC patients have a distinctive gene signature as compared to the monocytes isolated from HD suggesting that, during cancer progression, monocytes activate specific transcriptional programs that can be, in turn, used as potential biomarkers." (PMID 31533831, 2019). "For the CD15+ CD14- MDSC population (which has been described as another important subpopulation regulating in a negative manner the immune responses in some cancer patients), samples of diabetics and nondiabetics show the presence of this population in low frequency." (PMID 31915708, 2019). "Therefore, as whole blood staining of fresh blood is becoming more standard practice, this will no doubt improve the prospect of using CD14+HLADRlo/neg monocytes as a biomarker for understanding responses to cancer immunotherapy." (PMID 31191529, 2019). "Using the improved method, we obtained CD14-ML from all samples, regardless of whether the donors were healthy individuals or cancer patients." (PMID 27050553, 2016).
cancer (continued). "However, no detectable CD14 expression was observed in PMNs from healthy donors or cancer patients." (PMID 38385073, 2024). "Another study characterized the heterogeneity of PMNs in cancer by using single-cell RNA-seq, single-cell mass cytometry by time-of-flight (CyTOF), flow cytometry, and functional analysis and suggested that PMN-MDSCs in mice could be identified based on CD14 expression." (PMID 38385073, 2024). "This increased percentage of CD14+CD80- can be explained by the polarization of macrophages to the M2 phenotype that highly expressed the CD163 receptors may be due to the secretion of adipocytes having myoCAF-like phenotype and cancer promoter microenvironment." (PMID 39072314, 2024). "In fact, circulating autologous CD14+ cells are the progenitor of resident NLCs and the baseline upregulation of Siglec‐10 might reflect the M2‐like immunosuppressive profile of NLCs within TME, where they interact with CD24+ cancer cells, receiving anti‐phagocytic stimuli." (PMID 37654003, 2023). "However, we could not exclude the possibility that these CD14+ monocytes were immunosuppressive MDSC found in cancer patients that could actively suppress the T-cell activation." (PMID 36536403, 2022). "Besides, decreased M2 polarization of CD11b+CD14+HLA-DRhi monocytes in the peripheral circulation was also correlated with better clinical outcome, which is consistent with previous reports that increased abundance of MDSC and M2 MΦ/Mo correlated with poor prognosis in cancer patients." (PMID 26579227, 2015). "However, CD14+CD16++ cells are the minor population consisting of approximately 5–10 % of total monocytes, and nonproliferating cells may be very limited in numbers that are required for adoptive immunotherapy of cancer." (PMID 23180014, 2013). "CCR2 was expressed on more than 60% of monocytes of classical CD14+CD16- subset, and the minimal expression level of CCR2 was observed in non-classical CD14-CD16+ subset in both healthy donors and cancer patients." (PMID 36733385, 2022). "For example, not all clusters were uniformly decreased in cancer, with a population of TBET- memory CD4 T cells (P1_28) and CD14- CX3CR1 + monocytes (P2_25) being elevated in cancer." (PMID 36307410, 2022). "Recent data interrogating the TCGA show upregulation of TGF-β1 in a number of cancers including CRC and this correlates with the markers expressed on M-MDSCs, CD14 and CD33, but not with the G-MDSC marker CD66b (PMN-MDSCs are CD33dim rather than the high expression seen on M-MDSCs)." (PMID 34727230, 2022). "Using PPI analysis, the critical pathway of functional genes was found involved in the hematopoietic cell lineage and transcriptional misregulation in cancer, including HOXA10, MEIS1, FLT3, CD14, PROM1, RUNX2, and RUNX1 (data not shown), indicating the dominant roles of HOXA and MEIS1 in MLL-R ALL." (PMID 36276286, 2022). "Compared to HD, there was a significant increase in the percentage of c-FLIP+CD14+ cells in PDAC but not in NET patients, suggesting that c-FLIP might constitute a biomarker for some cancers." (PMID 30518925, 2018). "However, individual effects of the different cancer cell lines were detected in cultures without cytokines, as significant downregulation of MHC class II and upregulation of CD206 and CD14 expression were observed between monocytes polarized by TCM from MIA PaCa-2 and MCF-7." (PMID 34451433, 2021).
bacterial infection (73 papers, 2008 to 2026). "Presepsin (PSP), a 13 kDa N-terminal fragment of soluble CD14 expressed in the acute phase of bacterial infection, represents a useful diagnostic biomarker in sepsis." (PMID 34943556, 2021). "Because its precursor CD14, expressed on the surface of phagocytes, is internalized during bacterial phagocytosis, the processed subtype presepsin has strong association with bacterial infections." (PMID 28056845, 2017). "Moreover, a CD14 deficient animal model exhibits higher bacterial disease severity." (PMID 24139637, 2013). "For instance, the expression of miR-2285 family members were also identified in immune related tissues during bacterial infections, such as mammary epithelial cells, alveolar macrophages and CD14 + monocytes." (PMID 41507779, 2026). "The left panel shows that under bacterial infection, CD14 mediates the activation of the MAPK pathway in macrophages, which further induces the phosphorylation of p38, JNK, and ERK." (PMID 41246296, 2025). "Among emerging tools for differential diagnosis, presepsin (soluble CD14 subtype) has shown potential in identifying serious bacterial infections in children with concurrent SARS-CoV-2 exposure." (PMID 40430232, 2025). "LBP aids the immune response to bacterial infections by binding LPS, enabling its detection by CD14 and Toll-like receptors, which initiate inflammation." (PMID 40027189, 2025). "Several innate immune signaling pathways are activated during bacterial infection, including Toll-like receptors (e.g.CD14/TLR4) and Nod-like receptors." (PMID 40114913, 2025). "PSP, derived from soluble CD14, reflects the activation of monocytes/macrophages in response to bacterial infections." (PMID 38928726, 2024). "Our study reveals consistent upregulation of the CD14 gene in the severe manifestations of both viral and bacterial infections." (PMID 38892107, 2024). "Recently, Presepsin (PSEP), also known as soluble CD14, has demonstrated potential as a prognostic biomarker for severe bacterial infections." (PMID 39441646, 2024). "In a bacterial infection, CD14+ cells will recognize the lipopolysaccharides (LPS) found in the bacterial cell wall of gram-negative bacteria to trigger an immune response." (PMID 38892107, 2024). "In parallel with this, previous studies have reported that LPS induces de novo synthesis of CD14 and promotes the translocation of CD14 from the cytoplasmic reservoir to the surface membrane of mature neutrophils during bacterial infection." (PMID 37566062, 2023). "A new and promising biomarker is presepsin, which is a soluble CD14 subtype that is released by monocytes and macrophages in response to bacterial infection." (PMID 36978356, 2023). "CD14 acts as a receptor for bacterial lipopolysaccharide and plays a role in mediating the innate immune response to bacterial infection." (PMID 37214419, 2023). "Although our studies demonstrate that CD14-expressing murine MSCs exhibit enhanced antibacterial properties in vitro, future studies involving in vivo mouse models of bacterial infection need to be performed to determine their potential clinical utility." (PMID 35141503, 2022). "TLR4 and its co-receptors MD2 and CD14 are required for immune response to fungal and bacterial infection by recognition of microbial cell wall components, making it a prime target for drug development." (PMID 35208698, 2022). "Similar studies have also reported LRR as the important domain against bacterial infections in case of CD14 molecule in cattle, goat, and buffalo." (PMID 34970593, 2021). "Since it is produced by direct interaction of bacteria ligands, such as lipopolysaccharide with CD14, a surface receptor on monocyte, it can be detected in early phase of bacterial infection." (PMID 34943556, 2021). "The activation of PMNLs during bacterial infections in vivo and by stimulants such as LPS and fMLP in vitro leads to a strong increase in CD14 cell surface expression." (PMID 33799511, 2021).
bacterial infection (continued). "In our lab, earlier we had studied immunogenetics against bacterial disease with identified immune response molecule such as CD14 gene in goat, cattle, and buffalo." (PMID 34970593, 2021). "Upon stimulation and in patients with severe bacterial infections, CD14 surface expression is strongly increased." (PMID 33799511, 2021). "Previous studies have shown that TCP-25 targets LPS and CD14, leading to the inhibition of inflammation during bacterial infection." (PMID 34424043, 2021). "CD14 mediates the lipopolysaccharide (LPS)-induced host protection against bacterial infections and CD16 is an Fc-receptor involved in antibody-mediated phagocytosis." (PMID 31151162, 2019). "CD14 involvement in the host defence against viral and bacterial infections has been investigated in several experimental models." (PMID 29899248, 2018). "Corneal fibroblasts sense bacterial infection through Toll-like receptor (TLR)–mediated detection of a complex of LPS with soluble cluster of differentiation 14 (CD14) and LPS binding protein present in tear fluid." (PMID 28832498, 2017). "Generally, CD14 on monocytes is considered to have a protective role against viral and bacterial infections." (PMID 27252945, 2016). "The impact of LukAB in killing human monocytes was also tested using live bacterial infection of purified CD14+ primary human monocytes." (PMID 26069969, 2015). "It is well recognized that CD14 is crucial for innate immune responses to bacterial infection as well as in the initiation of cytokine cascades." (PMID 23338226, 2013). "Using an intra-mammary infection as a model in vivo bacterial infection, we present the first in vivo evidence that 1α-OHase expression is upregulated in CD14+ cells that are at the site of a bacterial infection." (PMID 21124742, 2010). "Normal CD14 is a high-affinity receptor for lipopolysaccharide and is a glycoprotein expressed on the surface membranes of white blood cells, and its soluble subtype appears to increase in severe bacterial infections." (PMID 38539385, 2024). "Finally, our data also confirm the important role of CD14 on the phagocytic activity of those NPC when they are recruited into the inflammatory site in patients with an overwhelming bacterial infection." (PMID 37566062, 2023). "Additionally, with the emergence of molecular diagnostic techniques, promising lipid biomarker such as LPS, LTA, LBP and the immunologic biomarker soluble CD14 subtype, known as presepsin, for the detection of bacterial infections have been found." (PMID 34983426, 2022). "Interestingly, it is more expressed in the blood than in the brain, and it is induced in CD14+ monocytes upon bacterial infection (TPM ranging from 50 to 150)." (PMID 30610612, 2019). "The low levels of soluble CD14 and Endocab found in our study may suggest that infants were less exposed to intestinal bacterial infection." (PMID 29281659, 2017). "For example, ABCG2 gene is responsible for the active secretion of clinically and toxicologically relevant substrates into the milk and soluble CD14 in colostrum and milk acts as a sentinel molecule and an immune modulator, which provide innate responses against bacterial infections in the calf." (PMID 27441113, 2016). "The identified variations and association data have provided information that may shade more light on cell surface expression of CD14 by neutrophils, which are needed to control bacterial infections." (PMID 18691417, 2008). "Our SNP and association analyses have provided baseline information that may be used at defining the role of CD14 in mediating bacterial infections." (PMID 18691417, 2008). "The results may provide baseline information that may be used in candidate gene studies aimed at defining the role of CD14 in mediating bacterial infections." (PMID 18691417, 2008).